USP8 (ubiquitin specific peptidase 8)
Diseases named in the same sentence as USP8 in open-access papers (continued):
Sharing a sentence is not in itself a finding about the gene and the disease.
cancer (continued). "At present, it is still poorly understood if USP8 can contribute to survival of cancer cells independently of their drug sensitivity." (PMID 36578788, 2022). "Taken together, our findings demonstrate that a conserved Usp8-Tak1 module promotes tumor cell migration, and provides USP8 as a potential therapeutic target for cancer treatment." (PMID 35361778, 2022). "Taken together, our findings demonstrate that a conserved Usp8-Tak1-JNK axis promotes tumor cell migration, and providing USP8 as a potential therapeutic target for cancer treatment." (PMID 35361778, 2022). "Studies further reveal that the anti-cancer potential of USP8 inhibition is due to downregulation of several TKRs." (PMID 34081623, 2021). "This is supported by previous reports emphasizing the important role of USP8 in cancer growth, survival and invasion." (PMID 34081623, 2021). "Our work together with other reports confirm the potential of USP8 inhibition to overcome cancer resistance." (PMID 34081623, 2021). "ML364 has been identified as a potential small molecule inhibitor of USP2 with an IC50 of 1.1 μM, which induces cellular cyclin D1 degradation leading to cell-cycle arrest in HCT116 cancer cell lines and also has a lower affinity to USP8." (PMID 32549302, 2020). "The role of USP8 in the cancer progression has been reported in several types of cancers." (PMID 40410130, 2025). "USP8, a ubiquitin-specific protease, plays a prominent role in the endosomal sorting of a wide range of transmembrane receptors and is a promising target in cancer therapy." (PMID 39576689, 2024). "Strikingly, USP8 plays a dual role in controlling PD-L1 levels in distinct cancer types." (PMID 38715050, 2024). "In this regard, USP8 may lead to cancer immune evasion as it supports regulatory T cells and suppresses T cell functions." (PMID 39430244, 2024). "To confirm whether USP8 suppression enhances the anti-cancer activity of erastin in vivo, we stably knocked down USP8 in NCI-H1299 cell line by lentiviral vector." (PMID 37051673, 2023). "Although USP8 depletion suppresses cell proliferation in various cancer cells and induces cell death in some cell lines, whether a direct connection exists between USP8 and ferroptosis remains unknown." (PMID 37051673, 2023). "A recent study showed that USP8 might be an immunomodulatory target that enhances the efficacy of anti-PD-1/PD-L1 in treating human carcinomas." (PMID 36644233, 2023). "As the elevated EGFR, PI3K/Akt, and NF-kB activation is considered for the possible causes of developing chemoresistance/docetaxel resistance in cancer cells so USP8 silencing might also be a thinkable way to overcome docetaxel resistance for PCa." (PMID 36338727, 2022). "Together, these studies demonstrate that USP8 might play a critical role in promoting tumorigenesis and suppressing CD8+ T-cell function, which highlights USP8 could be a potential therapeutic target in human cancers." (PMID 35361799, 2022). "The overexpression of USP8 in cancer cells is known to promote cell growth." (PMID 35631459, 2022). "9-Oxo-9H-indeno[1,2-b]pyrazine-2,3-dicarbonitrile and analogs: 9-Oxo-9H-indeno[1,2-b]pyrazine-2,3-dicarbonitrile and its analogs have been identified by high-throughput screens as selective USP8 inhibitors that show anti-proliferative and pro-apoptotic activities in various cancer cell lines." (PMID 32549302, 2020). "USP8 inhibitors could effectively antagonize the TGF-β/Smad signaling pathway in cancer cells, decrease the stability of TβRII and the number of TbRII + crEvs, thereby preventing tumor-induced exhaustion of CD8 + T cells and activating anticancer immunity, thus reducing cancer size and metastasis." (PMID 38884843, 2024). "Moreover, studies have shown that Ubiquitin-specific peptidase 8 (USP8) plays an important role in regulating ferritinophagy and ferroptotic responses in cancer cells, revealing that USP8 could be a viable target for cancer therapies using ferroptosis." (PMID 38262996, 2024).
cancer (continued). "Therefore, USP8 has become increasingly considered as a potential anti-cancer therapeutic target." (PMID 36816802, 2023). "Taken together, these results suggest that USP8 inhibition by either the pharmacological inhibitor DUBs-IN-2 or genetic depletion could dramatically elevate the PD-L1 protein abundance largely at the posttranslational level in cancer cells." (PMID 35361799, 2022). "Hence, our study not only provides a molecular insight but also reveals a potential therapeutic strategy that targeting the immunomodulatory deubiquitinase USP8 might enhance the efficacy of anti-PD-1/PD-L1 in treating human cancers." (PMID 35361799, 2022). "Inhibitors of ubiquitin-specific peptidase 8 (USP8) and DUB-IN-3 have shown the most potent anti-cancer activities." (PMID 40959280, 2025). "From other cancers it is also reported that besides USP28, the deubiquitinases USP7, USP8, USP10 and USP11 interact with NICD and regulate NOTCH1 signaling." (PMID 40456839, 2025). "Ubiquitin-specific peptidase 8 (USP8), a member of DUB, regulates various substrates such as SQSTM1, P27, ESCRT-III, and c-Met in cancers." (PMID 38973004, 2024). "It is found that the inhibitor of ubiquitin specific peptidase 8 (USP8) and DUB‐IN‐3 shows the most effective anti‐cancer responses." (PMID 37867237, 2023). "The suppression of USP8-SQSTM1-NCOA4-ferritin axis through up-regulating ferritinophagy and intracellular iron levels sensitized cancer cells to ferroptosis." (PMID 37051673, 2023). "Additionally, DUB-IN-3, the inhibitor of ubiquitin specific peptidase 8 (USP8), shows effective anti-cancer responses." (PMID 41059334, 2025). "USP8 and NOTCH2 are well-known oncogenes that are frequently overexpressed in human cancers." (PMID 39456581, 2024). "Both USP8 and NOTCH2 are frequently overexpressed in human cancers." (PMID 39456581, 2024). "Therefore, our results corroborate the oncogenic properties of USP8 in GBM tumorigenesis and advocate it as an achievable anti-cancer target for future development." (PMID 36816802, 2023). "In addition, USP8, USP15, USP9X and USP18 are also being reported by a growing number of top research institutes for their vital immunomodulatory functions in cancer progression." (PMID 37658402, 2023). "To evaluate the effect of the altered expression of the CFA30 genes on cancer cell proliferation, we assessed the proliferation capability of canine MM cancer cells after silencing TRPM7, SPPL2A, GABPB1, and USP8 genes using colorimetric cell proliferation assays." (PMID 35053440, 2022). "DUBs are critical key players in diverse processes such as (i) spermatogenesis (e.g. USP2, USP8, USP9y, USP14, USP26, Uchl-1, Uchl-3 and CYLD), (ii) cancer biology (e.g. USP7, USP10 and USP11), and (iii) stemness and differentiation (e.g. USP7, USP9x, USP22, USP44 and Psmd14)." (PMID 28659380, 2017). "Notably, the inhibition of USP8 in lung squamous cancer tissues leads to an increase in PD-L1 protein levels, indicating a negative correlation between USP8 and PD-L1 in these cancer tissues." (PMID 38474186, 2024). "Besides OTUB1, other DUBs, such as USPs family (USP1, USP7, USP8, USP15, USP22), OTUs family (OTUD7B, OTUD6B, A20, and OTUB2) and other DUBs have been identified to regulate the progression of various cancers and applied for clinical cancer therapy." (PMID 35715413, 2022). "However, in the group of cancer patients with high USP8 expression, a higher level of CTL showed a worse patient survival, suggesting that a high level of USP8 might lead to T-cell dysfunction." (PMID 35361799, 2022). "Interestingly, our unbiased DUB screening also revealed that USP8 is also an important modulator in the Hippo pathway in TNBC, which also add knowledge for its role in cancer biology, while targeting USP8 could block several oncogenic pathways and be of great significance in cancer therapeutics." (PMID 41565619, 2026). "However, whether USP8 is involved in regulating cancer immunotherapy has not been reported." (PMID 35361799, 2022).
cancer (continued). "While the relationship between BRUCE, USP8, and NRDP1 has not been established in cancer cells, it is noteworthy that elevated levels of BRUCE are associated with worse outcomes in CaP patients." (PMID 34503235, 2021).
infection (3 papers, 2023 to 2025). The state of being infected such as from the introduction of a foreign agent such as serum, vaccine, antigenic substance or organism. "Hence, USP8 is proposed to suppress autophagic flux during infection with Salmonella, and its inhibition is associated with an induced clearance of bacteria." (PMID 37026055, 2023). "The results showed that EMCV infection dramatically induced the phosphorylation of USP8, as gauged by antibodies against pan‐phospho‐serine/threonine/tyrosine." (PMID 40525588, 2025). "As proof of principle, we have validated one of the enzymes significantly downregulated during infection with Salmonella, USP8." (PMID 37026055, 2023). "The presence of Salmonella Pathogenicity Island-2 (SPI-2) was required for infection-induced USP8 downregulation during infection." (PMID 37026055, 2023). "To discover the USP8 role in infection, we used a chemical inhibition of USP8 by DUBs-IN-2 inhibitor." (PMID 37026055, 2023). "In summary, USP8 inhibition has been shown to reduce the autophagy protein p62 during infection with Salmonella, which is correlated with increased autophagy flux." (PMID 37026055, 2023). "Additional infections performed in RAW 264.7 murine macrophages indicated similar results, where USP8 inhibitor DUBs-IN2 treatment was associated with a reduced number of Salmonella in the treated cells." (PMID 37026055, 2023). "To further validate these findings, we knocked down Usp8 in Usp8fl/fl mouse embryonic fibroblast (MEF) cells via infection with Cre lentivirus and found that the EMCV‐induced expression of Ifnb1 and Cxcl10 and the EMCV‐induced phosphorylation of TBK1 and IRF3 were significantly impaired." (PMID 40525588, 2025). "Some of these results showing the role of USP8 inhibition in regulating autophagy were replicated in HeLa cells, although it is essential to note that infection in epithelial HeLa cells might represent a separate mechanism compared to macrophages." (PMID 37026055, 2023). "The FAM168B, RAF1, HESX1, USP8, C2CD5, PIGC, ENSGALG00000053041, and ENSGALT00000092369 were found to be top driver genes shared among dpi, body weight post-infection, and propionate and valerate cecal contents." (PMID 36902251, 2023). "The CFUs of intracellular bacteria were enumerated after 2 hours and 24 hours post-infection (hpi), indicating that DUBs-IN2 USP8 inhibitor leads to a significant reduction of CFUs." (PMID 37026055, 2023). "While USP8 inhibition led to an increase in LC3 puncta in the absence of infection, the infection process further increased the increase in LC3 puncta." (PMID 37026055, 2023). "To determine if inhibition of the USP8 protein leads to an overall decrease in bacterial survival in macrophages, we performed an infection of THP-1-derived macrophages using GFP-expressing S. Typhimurium and the treatment with USP8 selective inhibitor DUBs-IN2." (PMID 37026055, 2023). "We then examined the association between USP8 and MDA5 and found that USP8 specifically interacted with MDA5 but not with other related proteins, such as RIG‐I, and that their association was potentiated after EMCV infection, but not Poly(I:C) HMW." (PMID 40525588, 2025). "Since the expression of SPI-2 appeared to be important in the regulation of USP8 expression, we also verified that the inhibition of USP8 in infections with Salmonella not expressing SseV that is therefore deficient in SPI-2, did not affect intracellular CFU number." (PMID 37026055, 2023). "While the level of USP8 in THP-1 macrophages infected with wild-type S. Typhimurium was diminished, the infection with ΔssaV did not lead to the downregulation of USP8, although the levels of intracellular bacteria were comparable for both strains." (PMID 37026055, 2023).
neurodegenerative disease (3 papers, 2019 to 2025). A disorder of the central nervous system characterized by gradual and progressive loss of neural tissue and neurologic function. "Thus, important prerequisites for compound optimization and drug development exist for USP8 and can be readily exploited in aged-associated neurodegenerative disease models." (PMID 37190052, 2023). "Influencing neurodegenerative disease pathologies, mainly through its interaction with α‐Synuclein and mitochondrial quality control mechanisms, positions USP8 as a critical target for therapeutic intervention." (PMID 39840724, 2025). "The evolving narrative surrounding USP8's contributions to neurodegenerative disease pathology demonstrates the enzyme's potential as a therapeutic target." (PMID 39840724, 2025). "Inhibition of USP8 also serves as a potential avenue to enhance proteasomal or autophagosomal degradation of aggregated proteins in neurodegenerative diseases." (PMID 31845722, 2019). "Moreover, inhibition of USP8 may serve as a potential avenue to enhance proteasomal or autophagosomal degradation of aggregated proteins in neurodegenerative diseases." (PMID 31845722, 2019).
hematological malignancies (1 paper, 2025). "For USP8 so far, no role in hematological malignancies has been reported." (PMID 40456839, 2025).
movement disorder (1 paper, 2022). Neurological conditions resulting in abnormal voluntary or involuntary movement, which may impact the speed, fluency, quality and ease of movement. "More relevant to movement disorders, USP8 may control alpha-synuclein ubiquitination and clearance via the proteasome." (PMID 35897705, 2022).
USP8 also shares sentences with these, for which no sentence is quoted: renal cell carcinoma (2 papers); adrenal adenomas (1); Adrenal Cushing’s Syndrome (1); Aicardi–Goutières syndrome (1); breast tumor (1); cardiomyopathy (1); Carney complex (1); craniopharyngioma (1); dermatomyositis (1); DICER1 syndrome (1); esophageal squamous cell carcinoma (1); hereditary spastic paraplegia (1); hyperlipidemia (1); Lewy body disease (1); lipodystrophy (1); liver diseases (1); Lynch syndrome (1); mesenchymal neoplasms (1); microphthalmia (1); multiple endocrine neoplasia type 1 (1); multiple myeloma (1); neurological disorders (1); pancreatic ductal adenocarcinoma (1); pituitary (1); pituitary carcinomas (1); pituitary hormone deficiency (1); pituitary-dependent Cushing's disease (1); sarcoma (1); somatotroph adenomas (1); Stroke (1).
A further 4 diseases each share a sentence with USP8 in 1 paper.